PROX1 (prospero homeobox 1)
Diseases named in the same sentence as PROX1 in open-access papers (continued):
Sharing a sentence is not in itself a finding about the gene and the disease.
hepatocellular carcinoma (continued). "We evaluated the staining of PROX1 in the cytoplasm, whereas in the previous studies of CRC, hepatocellular carcinoma (HCC), and gliomas, only the staining in tumor cell nuclei were evaluated." (PMID 27411302, 2016). "We also previously documented that high PROX1 protein expression in primary hepatocellular carcinoma (HCC) tissues was correlated with worse patient survival, in addition, PROX1 promoted HCC cell metastasis in vitro and in vivo." (PMID 24797520, 2014). "Furthermore, in hepatocellular carcinoma (HCC), the adapter protein PROX1 can promote NF-κB signaling by recruiting USP7 to the p65-p50 complex and facilitating p65 deubiquitination." (PMID 39767641, 2024). "Furthermore, Prox1 upregulated expression of hypoxia-inducible factor-1α (HIF-1α), thus promoting hepatocellular carcinoma metastasis." (PMID 29050214, 2017). "Manipulating PROX1 levels can switch transformed hepatocytes between cholangiocarcinoma (CCA) and hepatocellular carcinoma (HCC) fates." (PMID 39948437, 2025).
type 2 diabetes (21 papers, 2010 to 2023). "Surprisingly, in the group with the PROX1 CC genotype and a higher risk of type 2 diabetes mellitus, we found significantly lower food consumption, but higher accumulation of visceral fat." (PMID 25601634, 2015). "There was a significant difference (p = 0.039) in distribution of the studied PROX1 C allele (χ2 = 4.26) between the subjects with normal glucose levels and those with type 2 diabetes mellitus—48.8 versus 58.2 %, respectively." (PMID 25601634, 2015). "The large meta-analyses of genome-wide association studies have confirmed that the rs340874 single-nucleotide polymorphism (SNP) in PROX1 gene is associated with fasting glycemia and type 2 diabetes mellitus." (PMID 25601634, 2015). "Reduced expression of the transcription factor, prospero homeobox 1 (Prox1), by cis-regulatory variants altered beta cell insulin secretion which conferred susceptibility to type 2 diabetes." (PMID 23542897, 2013). "The associations of ADCY5 and PROX1 loci with type 2 diabetes also reached genome-wide significance." (PMID 21747906, 2011). "Further adjusting age, gender and BMI as confounders found PROX1 rs340874 was associated with type 2 diabetes (p = 0.0391)." (PMID 21103350, 2010). "In line with this, we found that the type 2 diabetes risk variant in the neuronal progenitor PROX1 gene was associated with decreased risk of severe DR in offspring of individuals exposed to famine, while this variant increased the PDR risk in the unexposed group." (PMID 35600617, 2022). "In addition to these human congenital diseases, PROX1 mutation or SNPs are associated with adult-onset obesity or type 2 diabetes." (PMID 32640757, 2020). "Our study revealed other postprandial disruptions in the high-risk PROX1 genotype carriers, which may be a part of potential type 2 diabetes disease pathways." (PMID 31010169, 2019). "Moreover, in the logistic regression model, the PROX1 CC genotype was associated with type 2 diabetes mellitus risk [OR 2.8 (1.1–8.7), p = 0.044] when adjusted for age, sex, BMI, HOMA-IR and VAT/SAT ratio (recessive model)." (PMID 25601634, 2015). "Expression of PROX1 is shown to be downregulated in islets from type 2 diabetes donors as compared to controls." (PMID 35600617, 2022). "A DMR was identified in one of the type-2 diabetes genes (PROX1) and differential methylation of the six CpG sites in KCNQ1 were validated by pyrosequencing (see later)." (PMID 25651499, 2015). "More recently, another study in a case-control sample of Chinese also replicated the associations of DGKB, MADD, GLIS3, PROX1 and IGF1 with type 2 diabetes and/or glycemic traits." (PMID 21747906, 2011). "In addition to novel shared SNPs, we further highlight one single-trait-driven SNP of interest, rs72753599, located near PROX1, a gene known to alter beta cell insulin secretion, which was shared by type 2 diabetes, T2DMadjBMI, FGadjBMI and PCOS." (PMID 35771237, 2022). "Importantly, several single nucleotide polymorphisms (SNPs) present in intronic regions of PROX1 were suggested to modulate PROX1 expression levels with potential involvement in the pathogenesis of type 2 diabetes." (PMID 32370142, 2020). "Prox1 is involved in muscle fiber conversion, adult-onset obesity, and type 2 diabetes." (PMID 31569476, 2019). "Of these loci, only GCK, MTNR1B, DGKB, GCKR, ADCY5 and PROX1 (besides TCF7L2 and SLC30A8) were associated with type 2 diabetes at genome-wide significance levels, with several others (but not all) showing a consistent trend but not meeting the same stringent statistical threshold." (PMID 22984506, 2012). "The only nominal association with diabetes incidence was found for the glucose-lowering allele at PROX1 (P = 0.02), in a direction opposite to that reported in case-control analyses in MAGIC, where the C allele increased type 2 diabetes risk (odds ratio 1.07 [95% CI 1.05–1.09], P = 7.2×10−10)." (PMID 22984506, 2012).
type 2 diabetes (continued). "It is interesting to note that, excluding the TCF7L2 SNP, three of the four variants most strongly associated with type 2 diabetes in the MAGIC study (MTNR1B rs10830963, PROX1 rs340874 and GCKR rs780094) have odds ratios of less than one in our South Asian populations." (PMID 21949744, 2011). "Large-scale meta-analyses of genome-wide association studies have recently confirmed that the rs340874 single-nucleotide polymorphism in PROX1 gene is associated with fasting glycemia and type 2 diabetes mellitus; however, the mechanism of this link was not well established." (PMID 25601634, 2015). "We showed SNPs from seven loci, including GIPR, TCF7L2, MADD, CRY2, GLIS3, PROX1 and SLC30A8, had an effect on type 2 diabetes in our samples." (PMID 21103350, 2010). "The link between type 2 diabetes mellitus and PROX1 is not well established; however, the two previous studies have suggested that potential type 2 diabetes mellitus disease pathways can be related to β-cell dysfunction." (PMID 25601634, 2015). "SNPs in or near MADD, ADRA2A, PROX1, FADS1, C2CD4B, IGF1, and IRS1 did not exhibit significant associations with type 2 diabetes or related glycemic traits (P≥0.10)." (PMID 21747906, 2011).
lymphedema (18 papers, 2019 to 2026). Excess fluid collection in tissues, causing swelling. "Although PROX1 has long been recognized for its role in lymphatic development, few human studies have directly linked PROX1 mutations to primary lymphedema." (PMID 40678385, 2025). "This case presents an unusual instance of primary lymphedema affecting both the upper and lower limbs, associated with a novel mutation in PROX1." (PMID 40678385, 2025). "Prox-1 is a major transcription factor of lymphatic development and mutations of the PROX1 gene have been reported in lymphedema patients." (PMID 34733847, 2021). "Two PROX1 variants were recently identified in lymphedema patients." (PMID 35806420, 2022). "Given the role in murine models of Prox1 in the accumulation of adipose tissue associated with abnormal lymph leakage, we thought it would be interesting to consider this gene in lymphedema screening." (PMID 32757260, 2020). "Our results suggest that PROX1 is a new candidate gene for predisposition to lymphedema." (PMID 32757260, 2020). "In conclusion, the results of our study are in line with the hypothesis that heterozygous variants of PROX1 caused predisposition to lymphedema in our patients and that PROX1 should be considered as a new candidate gene for lymphedema in humans." (PMID 32757260, 2020). "It has been already shown that PROX1 is associated with defects affecting lymphatic vascular structure and function, which may lead to lymphedema and imbalanced eicosanoid metabolism." (PMID 31010169, 2019). "VEGFC and PROX1 play key roles in lymphangiogenesis and lymphatic endothelial identity, with therapeutic potential for lymphedema and tissue repair, respectively." (PMID 41214597, 2025). "The identification of a novel, heterozygous PROX1 mutation in this patient adds to a limited but emerging body of evidence implicating PROX1 in both syndromic and non-syndromic forms of lymphedema." (PMID 40678385, 2025). "Mutations in the GATA2 gene, the transcription factor controlling Prox1 and FOXC2 expression, cause primary lymphedema with myelodysplasia." (PMID 40766782, 2025). "Firstly, we did not investigate the involvement of other proteins known to mediate pathologic changes in lymphedema, such as TGFβ and PROX-1, in both male and female models." (PMID 39691094, 2024). "In particular, mutations in SOX18, PROX1, GATA2, and FOXC2 cause various forms of syndromic lymphedema." (PMID 35806420, 2022). "Lymphovenous valve insufficiency is a feature of several lymphedema mouse models with disruptions in genes including Prox1, Foxc2, Cx37, Gata2, Pdpn, or Clec2." (PMID 34055805, 2021). "The aim of the study was to define these patients’ genotypes and explore the role of the candidate gene PROX1 in lymphedema." (PMID 32757260, 2020). "This study concluded that the GATA2 mutations abolishing enhancer-binding resulted in the loss of valves due to reduced expression of PROX1 and FOXC2, and strongly suggests that a loss of valves leads to lymphedema in human patients." (PMID 32824219, 2020). "Focal delivery of Prox1 (a master regulator of lymphangiogensis) using tissue nanotransfection technology (TNT) in the murine tail model has been studied to experimentally prevent lymphedema." (PMID 40655942, 2025). "Mutations in SOX18 may indirectly regulate VEGFR3 expression by affecting Prox1, resulting in lymphedema." (PMID 40766782, 2025). "Moreover, although mutations in PROX1 are not directly linked to lymphedema in OMIM, several studies support its essential role in lymphangiogenesis." (PMID 35806420, 2022). "However, to our knowledge, no PROX1 variants have yet been described in association with lymphedema." (PMID 32757260, 2020). "Additionally, the mutations in GATA2 that underlie Emberger syndrome produced mutant GATA2 proteins that were unable to bind enhancer elements in both the PROX1 and FOXC2 genes that were active only in the valve cells, and only these mutations were associated with lymphedema in patients." (PMID 32824219, 2020).
lymphedema (continued). "In a mouse model of lymphedema, TNT was used prophylactically to deliver prospero homeobox 1 (Prox1), a master regulator of lymphangiogenesis, to the site of lymphatic injury." (PMID 40606909, 2025). "There was a tendency of more but not significantly increases in the expression of VEGF‐C, LYVE‐1, podoplanin, PROX‐1 and FLT4 in the lymphedema group in comparison to the normal group, suggesting that lymphangiogenesis occurs when lymphatic injury, tissue injury or lymphedema presents." (PMID 36176614, 2022). "Therefore, considering the importance of PROX1 in the development of lymphatic vessels, we decided to extend the analysis of our lymphedema patients who had turned out negative for a first set of genes, retesting them also for germinal variants of PROX1." (PMID 32757260, 2020).
gastric cancer (15 papers, 2012 to 2025). A primary or metastatic malignant neoplasm involving the stomach. "This study, therefore, aimed to explore the association between MMP14 and PROX1 and understand their potential as prognostic biomarkers in gastric cancer." (PMID 31560170, 2019). "We also found that nuclear PROX1 expression in gastric cancer tissue samples associates with diffuse‐type tumors." (PMID 31560170, 2019). "However, a high immunohistochemical PROX1 expression in gastric cancer patients' tissue samples has been paradoxically linked both to better and worse prognoses." (PMID 31560170, 2019). "Association of PROX1 with clinicopathological variables in gastric cancer patients." (PMID 28854215, 2017). "In addition to this oncogenic role of PROX1, it may in gastric cancer play several roles, as we found that high PROX1 expression was associated with a better prognosis." (PMID 28854215, 2017). "Another research supported the involvement of PROX1 as one of the main promoters of tumor invasion and metastasis in gastric cancer and suggested its role as a prognostic factor for such malignancies." (PMID 40660330, 2025). "PROX1 staining is also more intense in the areas of the invasion front, indicating PROX1 as a new tumor marker for gastric cancer." (PMID 35885529, 2022). "Altogether, these data suggest that PROX1 promotes lymphangiogenesis, proliferation, and gastric cancer development." (PMID 35885529, 2022). "Although studies of Prox1 in vascular pathobiology are scarce, cytoplasmic Prox1 has been detected earlier in human lens cells and thyroid and gastric cancers." (PMID 36064651, 2022). "The role of PROX1 in gastric cancer has been the subject of investigation in four studies, which, interestingly, lead to conflicting conclusions." (PMID 35885529, 2022). "The relationship between PROX1 expression and clinicopathological characteristics and prognosis in patients with gastric cancer (GC) remain controversial." (PMID 35346069, 2022). "MMP14 and PROX1 expressions were studied using immunohistochemistry in the patient samples and using immunoblotting and immunofluorescence in gastric cancer cell lines." (PMID 31560170, 2019). "To further explore the functional connection between MMP14 and PROX1 in gastric cancer, we silenced PROX1 in the AGS cells using two different siRNAs." (PMID 31560170, 2019). "In conclusion, this study confirms that a high MMP14 expression predicts worse survival in gastric cancer and, for the first time, shows that survival is worse if PROX1 specifically is low." (PMID 31560170, 2019). "More extensive laboratory experiments and analysis on other large, well‐defined patient cohorts are needed to further disentangle the functions and cross talk between MMP14 and PROX1 in gastric cancer." (PMID 31560170, 2019). "We then silenced PROX1 in the AGS cells to further explore the connection between MMP14 and PROX1 in gastric cancer, finding that siRNA transfection using two PROX1‐targeting siRNAs resulted in increased MMP14 protein levels in both cases." (PMID 31560170, 2019). "This stands in contrast to the oncogenic role of PROX1 previously found in gastric cancer and with the presumed connection between the nuclear PROX1 expression and a worse prognosis." (PMID 31560170, 2019). "This further indicates that PROX1 participates in governing the MMP14 expression in gastric cancer as well." (PMID 31560170, 2019). "This study confirms that a high MMP14 expression predicts a worse survival in gastric cancer, revealing for the first time that survival is particularly worse when PROX1 is low." (PMID 31560170, 2019). "MMP14 and PROX1 expressions were studied using immunohistochemistry in the patient sample and using immunoblotting and immunofluorescence in gastric cancer cell lines." (PMID 31560170, 2019).
gastric cancer (continued). "The aim of this study was to explore the association between matrix metalloproteinase 14 (MMP14) and prospero homeobox protein 1 (PROX1) and understand their potential as prognostic biomarkers in gastric cancer." (PMID 31560170, 2019). "The strengths of this study include the large patient cohort with reliable follow‐up information, validation of previous results, and the exploration of the roles of MMP14 and PROX1 in gastric cancer in both laboratory and clinical settings." (PMID 31560170, 2019). "Further, PROX1 overexpression reverses miR-489-mediated suppression of proliferation and invasion of gastric cancer cells." (PMID 28854215, 2017). "In contrast, we noted the opposite result, because gastric cancer patients with high PROX1 expression had a better survival than did those with low or no expression." (PMID 28854215, 2017). "The aim of this study was to determine the prognostic value of immunohistochemical staining of PROX1 in gastric cancer." (PMID 28854215, 2017). "We evaluated PROX1 expression in gastric cancer by immunohistochemistry of tumor-tissue microarrays including tumor specimens from 283 patients who underwent surgery at Helsinki University Hospital." (PMID 28854215, 2017). "In conclusion, our study shows that PROX1 expression serves as a marker of favorable prognosis in gastric cancer." (PMID 28854215, 2017). "Here we show that cancer-specific 5-year survival was significantly better for gastric cancer patients with PROX1-positive tumors." (PMID 28854215, 2017). "In a recent study of gastric cancer, also cytoplasmic PROX1 expression by IHC was evaluated and it correlated with mRNA amplification." (PMID 27411302, 2016). "In addition, LNCAROD enhanced migration and proliferation via targeting miR-181/PROX1 axis in gastric cancer cells." (PMID 37597098, 2023). "On the other hand, focusing on miR-489 re-expression could inhibit the deleterious effects of PROX1 in tumor expansion in gastric cancer." (PMID 35885529, 2022). "In gastric cancer, there is also a positive correlation between PROX1 expression and tumor grade." (PMID 35885529, 2022). "Similarly, in gastric cancer, elevated PROX1 expression levels were related to poor prognosis and to a high proliferation rate (assessed with the Ki-67 labeling index), and increased lymphatic vessel density." (PMID 35885529, 2022). "Therefore, this study aimed to investigate the relationship between MMP14 and PROX1 in gastric cancer and to explore their values as prognostic biomarkers." (PMID 31560170, 2019). "Thus, this study confirms that a high MMP14 expression predicts a worse survival in gastric cancer, revealing for the first time that survival is particularly worse when PROX1 is low." (PMID 31560170, 2019). "In gastric cancer, high cytoplasmic PROX1 expression is an independent marker of better prognosis." (PMID 28854215, 2017). "In gastric cancer, PROX1 may promote tumor progression by inducing cancer-cell proliferation and lymphangiogenesis." (PMID 28854215, 2017). "The aim of this study was to investigate the prognostic role of PROX1 expression in gastric cancer." (PMID 28854215, 2017). "PROX1 expression when, appearing in gastric cancer tissue, may serve as a potential prognostic factor and treatment target." (PMID 28854215, 2017). "Interestingly, miR-489 transfection reduces PROX1 protein in gastric cancer cells, and PROX1 silencing seems to inhibit proliferation." (PMID 28854215, 2017). "Furthermore, the expression of Prox-1 in the gastric cancer SGC-7901 cell line increased following 40 days of treatment with hBM-MSC-CM." (PMID 25663886, 2015). "However, studies on the role of PROX1 in tumorigenesis of other cancer types, like glioblastoma and gastric cancer, reported results contradictory to ours and the observed effect of PROX1 may be specific for thyroid cells." (PMID 31060342, 2019).